RNU1-39P (RNA, U1 small nuclear 39, pseudogene)
Gene: Small nuclear RNA gene on chromosome 5 (178,884,715 to 178,884,879, forward strand). Ensembl gene ENSG00000206624.
Homologues: Orthologues: chimpanzee U1 (100% identical), macaque U1 (91% identical), mouse Gm23330 (90% identical). Paralogues in human: RNU1-89P (92% identical), RNU1-1 (92% identical), RNU1-2 (92% identical), RNU1-27P (92% identical), RNU1-28P (92% identical), RNU1-3 (92% identical), RNU1-4 (92% identical), RNVU1-18 (92% identical), RNVU1-29 (92% identical), U1 (92% identical), RNVU1-28 (91% identical), RNVU1-7 (91% identical), and 134 more.